TF (transferrin)
Diseases named in the same sentence as TF in open-access papers (continued):
Sharing a sentence is not in itself a finding about the gene and the disease.
cancer (continued). "The typical necrosis features, such as formation of swollen cytoplasm, early loss of membrane integrity, and disintegration (swelling) of organelles, became more obvious in the cancer cells of the transferrin-treated group as treatments were repeated." (PMID 30202000, 2018). "For data exploration, multi-omics data such as SNV, CNV and gene expression can be visualized simultaneously in KEGG pathway maps, together with transcription factors-target genes (TF-TG) correlation and relationships among cancer driver genes." (PMID 29504910, 2018). "Transferrin (Tf), a glycoproteins over expressed on the surface of the cancer cells was used as a ligand to carry WT1-shRNA to tumor." (PMID 29861465, 2018). "In the meantime, a clinically approved PTT agent, protoporphyrin IX, was loaded into the transferrin shell, being able to be drawn upon by cancer cells for efficient PDT with NIR irradiation and luminescence bio-imaging." (PMID 29755355, 2018). "For this purpose, those cancer cells often overexpress receptors for transferrin (iron-transporting protein), and transferrin-conjugated nanocarriers can be effectively used to increase cellular uptake into these cells." (PMID 29891921, 2018). "The local radiofrequency hyperthermia combined with transferrin as a thermosensitizer dramatically reduced the size of cancer tissue as the treatment continued and completely eradicated cancer after 5 weeks of treatment." (PMID 30202000, 2018). "The transferrin-conjugated nanoparticle will be accumulating in the cancer cells in a receptor-mediated fashion." (PMID 30191515, 2018). "Our experimental data show that transferrin is able to selectively deliver ferric ion into cancer cells, and animal experiments reveal that using transferrin as a thermosensitizer in a radiofrequency hyperthermia eradicated cancer completely." (PMID 30202000, 2018). "Some proteins, e.g., transferrin and lactoferrin, can be specifically bound to receptor(s) highly expressed in considerable cancer cells via receptor-ligand interaction, enabling the construction of active targeted theranostic nanoplatforms." (PMID 29755355, 2018). "It has been well known that transferrin has a strong cancer-targeting ability, which means that in the presence of transferrin, concentration of ferric ion should be higher in cancer tissues than in normal tissues." (PMID 30202000, 2018). "Under-expression of TF in both, serum and cancer tissue samples, was also proved by a label-free LC-MS experiment." (PMID 30065196, 2018). "Considering these characteristics, we believe that transferrin is the ideal choice as a thermosensitizer for treating cancer using radiofrequency hyperthermia." (PMID 30202000, 2018). "As expected, repeated i. v. injection of transferrin into cancer-bearing mice resulted in a gradual increment of ferric ion concentration in cancer cells in a dose dependent manner." (PMID 30202000, 2018). "A study of NAF collected from 66 women found that cancer patients (particularly postmenopausal) have high levels of TF and FTN, compared to healthy women." (PMID 29344009, 2018). "Iron, delivered inside the cells by different carriers, such as transferrin, is crucial for cancer cells proliferation, survival and metastatic spread." (PMID 30112105, 2018). "In contrast, when combined with transferrin injection, radiofrequency hyperthermia resulted in massive necrosis in the cancer tissues." (PMID 30202000, 2018). "Because current radiofrequency hyperthermia are slightly effective in cancer treatment, development of transferrin as a thermosensitizer in radiofrequency hyperthermia would be a major progress in cancer treatment." (PMID 30202000, 2018). "Since the TF-antigen is an important marker in human carcinoma, the possibility that Jacalin can be used as an anti-TF antigen has been suggested." (PMID 29661177, 2018).
cancer (continued). "In order to improve the tumor-targeting properties of cisplatin, transferrin (Tf) was employed as a carrier to transfer cisplatin into cancer cells via transferrin receptor 1 (TfR1) mediated endocytosis." (PMID 28484093, 2017). "Our research group preliminary study found that the total flavonoids from Radix Tetrastigmae (TF) has a better anti HCC effect, can inhibit the release of inflammatory factors and cancer cytokines, compared with other compounds, TF advantage is very prominent." (PMID 28903343, 2017). "As increased cisplatin/TF ratio, delivery of Tf-cisplatin to cancer cells was more efficient, and Tf-cisplatin had better inhibition effect for cancer cells than free cisplatin under the same cisplatin concentration in general." (PMID 28484093, 2017). "The rate of proliferation of cancer cells is usually rapid with their high demand for iron than the normal cells, resulting in an increased expression of transferrin on the surface of cancer cells." (PMID 28230749, 2017). "Results showed that, compared with the PGE2 control group, both three concentrations of TF had an obvious inhibitory effect on the cancer cells and the inhibition was enhanced with increasing dose (P<0.01)." (PMID 28903343, 2017). "Enhancer of zeste homolog 2 (EZH2) was the most significantly enriched TF overlapping CpGs with higher methylation in the cancer tissues from our dataset (Fisher’s Exact Test, Bonferroni adj." (PMID 28412973, 2017). "More interestingly, TFR1 has been extensively studied as a delivery vehicle for anti-cancer drugs, either through its ligand, transferrin, or its monoclonal antibodies." (PMID 27802297, 2016). "Due to the ability of jacalin to recognize TF antigens, its use as a carrier protein in cancer treatment has been considered." (PMID 27119077, 2016). "TF-specific lectins are gaining clinical implications as they are increasingly known to inhibit cancer cell proliferation and metastasis in TF expressing cells." (PMID 27119077, 2016). "In summary, we have developed a novel theranostic drug delivery system based on hydrophobic IR780-loaded transferrin nanoparticles for cancer imaging and PDT/PTT synergetic phototherapy by a single NIR laser irradiation." (PMID 27263444, 2016). "A phase 1 clinical study reported a partial response of 87% after using cisplatin-conjugated transferrin to treat patients with advanced cancers." (PMID 27384479, 2016). "Herein, a simple multifunctional IR780-loaded nanoplatform based on transferrin was developed for targeted imaging and phototherapy of cancer compatible with a single-NIR-laser irradiation." (PMID 27263444, 2016). "All three peptides share similar glycosylation pattern: O-glycosylated threonine with a galactosamine-galactose moiety, β-D-Gal-(1→3)-α-D-GalNAc-(1→) Thr, also found in Thomsen-Freidenreich antigens (TF-antigens) expressed on a surface of cancer cells." (PMID 25713532, 2015). "The results are consistent with previous studies that transferrin increases cell proliferation in cancer cells." (PMID 26664465, 2015). "Then, by examining the expression patterns of each of the TF family members expected to bind to these motifs, we have predicted the TF that regulates specific sets of genes in the different cancer types." (PMID 25994056, 2015). "Dp44mT also induced a significant (p < 0.001) increase in 59Fe mobilization from MCF-7 cancer cells prelabeled with 59Fe-transferrin (51% of cellular 59Fe) relative to the control and similar results were also observed with its main metabolite, Dp4mT." (PMID 26623727, 2015). "Cancer cells crave iron; the increase in transferrin and decrease in ferroportin leads to an increase in the labile iron pool, providing additional iron to support cancer cell proliferation." (PMID 26536104, 2015). "More importantly, IgG antibodies elicited from this vaccine were found to cross-react with native TF epitopes of MCF-7 cancer cells." (PMID 25670999, 2015).
cancer (continued). "Nowadays, TF antigen-binding lectins have attracted considerable interest since they have potential applications in cancer diagnostics and therapy." (PMID 26076107, 2015). "One of these proteins is transferrin, which supports iron transport and is up regulated in cancer cells to meet increased iron demands." (PMID 26536104, 2015). "We then found that Adpa-Mn achieved its selectivity against cancer cells through the transferrin (Tf)-transferrin receptor (TfR) system, which is highly expressed in tumor cells." (PMID 25604962, 2015). "In the presence of transferrin, Cerium has a more significant effect on the mortality rate of cancer cells." (PMID 26664465, 2015). "CALAA-01 consists of siRNA against the M2 subunit of ribonucleotide reductase (RRM2), which is involved in the proliferation of cancer cells, and targeted to cancer cells via a human transferrin protein targeting ligand." (PMID 24472581, 2014). "Targeting TF expression in cancer cells is a promising and attractive method for finding new treatment options." (PMID 25477962, 2014). "Previous studies have shown that blood proteins interact with each other, and that in the case of cancer amounts of the (HSA-PPIX)-TF complex are increased." (PMID 24392106, 2014). "Artemisinin is the major sesquiterpene lactones in sweet wormwood (Artemisia annua L.), and its combination with transferrin exhibits versatile anti-cancer activities." (PMID 24887240, 2014). "Cancer cells up-regulate transferrin (Tf) receptor 1 (TfR1) expression on their surface to increase iron uptake from the iron transport protein, Tf." (PMID 25393531, 2014). "Cancer cell target: Epidermal growth factor receptor monoclonal antibody, epidermal growth factor, human epidermal receptor 2, transferrin, A10 aptamer, As1411 aptamer, cRGD, galactose, hyaluronic acid, folic acid, glycyrrhizin, etc." (PMID 25522316, 2014). "The comparison of sera of cancer patients and healthy volunteers provided peaks from three differentially detected proteins, complement component 3a des-Arg, alpha-1-antitrypsin and transferrin, with 95% sensitivity and 91% specificity." (PMID 24618180, 2014). "In OSCC, the anti-TFRC antibody is suspected to block the internalization of transferrin into cancer cells, and the resulting transferrin deficiency might block the cell cycle and/or induce apoptotic cell death due to the potentially abnormal transferrin requirements of cancer cells." (PMID 24890018, 2014). "It is reported that the anti-cancer effect of artemisinin in the presence of iron sources such as transferrin was increased several fold." (PMID 24887240, 2014). "In the present study, we investigated the anti-metastatic effect of total flavonoids of S. barbata (TF-SB) using the human hepatocarcinoma MHCC97H cell line to clarify the possible molecular mechanism of TF-SB in inhibiting cancer cell invasion." (PMID 23344202, 2013). "The functionalization of these NPs with ligand, that is, folate or transferrin, able to target cancer cells, can be used to enhance the antitumor activity and to increase the selectivity of the treatment." (PMID 23533771, 2013). "For the nine added TF genes, seven of them were reported to take part in apoptosis in various types of cancer or diseases; these seven TFs are STAT3, ETS1, LEF1, STAT4, E2F3, ATF3, and HMGA2, which have not been annotated by GO yet." (PMID 22952919, 2012). "Based on these data, nigrin b and ebulin l were conjugated to human transferrin to study their potential suitability for the construction of conjugates for cancer therapy." (PMID 22069717, 2011). "Transferrin, another protein associated with HER2-positive cancer, is essential for cell growth and iron-dependent metabolic activities including DNA synthesis, electron transport, and mitogenic signaling pathways." (PMID 22110952, 2011).
cancer (continued). "Compared with the direct treatment of cancer cells with cerium, the presence of transferrin assisted inhibition of cell proliferation by 20% and 40% in Hela and MCF-7 cells, respectively." (PMID 21589800, 2010). "In Hela cancer cells, at 10 μM concentration of cerium cell, the viability was reduced after 48 h and 72 h treatments, and in the presence of transferrin, the inhibitory effect of cerium on Hela cancer cell growth increased significantly." (PMID 21589800, 2010). "TF antigen is covered in normal epithelium by extensive glycosylation, sulphation and/or sialylation but expressed in unsubstituted form by most human cancer cells." (PMID 20565834, 2010). "Based on this data, we propose that a potential targeted strategy to ameliorate cancer incidence and progression, might be to interfere with transferrin-bound iron uptake by targeting the Tfr1 expression in hepatocytes." (PMID 39820815, 2025). "Transferrin (Tf) protein was employed as the hydrophilic protein component in the nanoparticles since it can target the Tf receptors that are overexpressed in a variety of cancer cells." (PMID 40005167, 2025). "animals and F. mortiferum and TRF (transferrin) in cancer patients." (PMID 41449037, 2025). "Collectively, our results have demonstrated that exosomal TF-Ag-α could serve as a robust and broadly applicable biomarker for early multi-cancer detection." (PMID 41374931, 2025). "Moreover, ligands such as transferrin (Tf), which are abundantly expressed on cancer cells, can bind to transferrin receptors (TfR) inherently present on EV surfaces, so enabling targeted delivery." (PMID 40530018, 2025). "The TF antigen is presented on the surface of most human cancer cell types and its interaction with galectins 1 and 3 leads to tumour cell aggregation and promotes cancer metastasis." (PMID 38318459, 2024). "NC-6300 has also been conjugated with an antitissue factor mAb (clone 1849) for targeted cancer therapy, since tissue factor (TF), an initiator of the extrinsic blood coagulation cascade, is frequently overexpressed in cancer cells and tumor vascular endothelium." (PMID 39204392, 2024). "Research has linked CA9 with the process of ferroptosis, suggesting it could counteract this iron-dependent form of cell death in various cancers by modifying transferrin endocytosis and stabilizing ferritin levels." (PMID 39351146, 2024). "The active targeting strategy of nanoparticles is mainly focused on the overexpression of many receptors such as epidermal growth factor, folate, transferrin, and integrin receptor present on the surface of vascular endothelial cells of cancer cells or tumors compared to normal cells." (PMID 39319107, 2024). "Functionalization of the surface of NPs by conjugation with appropriate targeting ligands, such as folate, transferrin, monoclonal antibodies (mAbs), peptides, carbohydrates, and aptamers, is an efficient strategy for specific and selective drug delivery to cancer cells or intracellular components." (PMID 39204392, 2024). "Thus, the transferrin delivery system (FT) has the ability to be formulated into a newer, improved cancer treatment method." (PMID 38558360, 2024). "Studies have found that TF upregulation can promote ferroptosis and inhibit cancer progression." (PMID 38410113, 2024). "Cancer cells affected TF expression in FB, while remaining weakly responsive to FB." (PMID 39318629, 2024). "TF genes play a regulatory role according to gene expression, which may lead to the production of cancer cells." (PMID 39650066, 2024). "In addition to cancer cells, stromal cells such as monocytes/macrophages, fibroblasts, and microvascular endothelial cells express TF in cancer lesions." (PMID 38473827, 2024). "However, the current study found the opposite result for predicting survival in patients with cancer cachexia: albumin had the most accurate prognostic value, followed by transferrin and prealbumin." (PMID 38438901, 2024).
cancer (continued). "Several methods existed to assess the nutritional status of cancer patients, along with numerous indicators for evaluating nutritional status, such as hematocrit, hemoglobin, albumin, transferrin, heme, serum creatinine, urine creatinine, and BMI, among others." (PMID 39464703, 2024). "Therefore, our study aimed to thoroughly investigate and compare the value of albumin, prealbumin and transferrin in predicting survival and QoL in patients with cancer cachexia." (PMID 38438901, 2024). "Lactoferrin (LF) is a glycoprotein of the transferrin (TF) family that can bind to TF receptors (TFRs) and LF membrane internalization receptors (LFRs) that are highly expressed on the surface of cancer cells and blood-brain barrier (BBB), thereby promoting entry into the cell nucleus." (PMID 38910887, 2024). "Some of the blood transport plasma proteins can also be uptaken by cancer cells via active targeting: cancer cells can selectively accumulate human serum albumin and transferrin because of the high expression levels of albumin-binding proteins (gp60 and SPARC) and transferrin receptors." (PMID 37299673, 2023). "However, more broadly, the general addiction of metastasizing cancer cells to the expression of TF dependency genes is indirectly targetable through transcriptional inhibition with JQ1." (PMID 37938582, 2023). "Importantly, the ZF-C2H2 TF showed a significantly higher polyploid/diploid cancer fold than the other genes from 10–17 phylostrata." (PMID 37047167, 2023). "CA9 may potentially affect the endocytosis of transferrin, thus affecting iron uptake by cancer cells." (PMID 36760347, 2023). "The cellular uptake studies revealed a significant increase in drug uptake upon the conjugation of transferrin to zein-based hybrid lipid nanoparticles, particularly in comparison with the control formulation and the drug solution on PC-3 and LNCaP cancer cell lines." (PMID 38004621, 2023). "We subsequently evaluated preferential iron uptake ability in PDAC samples with different expression levels of c-Jun, and we conducted an in vitro coculture experiment in which fluorescently labeled cancer cells were subjected to transferrin loading and imaging." (PMID 37143164, 2023). "Still, a general trend can be observed across all investigated indications of this review (HF, CKD, IBD, cancer) that serum ferritin and transferrin saturation (TSAT) are the two parameters mentioned most often and emphasized in all guidelines to define ID and guide treatment." (PMID 36617559, 2023). "Therefore, Lcn-2, a transferrin-independent iron carrier, allows cancer cells to acquire the additional necessary iron." (PMID 37958332, 2023). "Secondly, it caused a decrease in survival in Y79 cells compared to ARPE19 cells that were also infected, this may be due to the presence of transferrin and folate ligands and the presence of numerous receptors for these ligands on the surface of cancer cells." (PMID 38102193, 2023). "Examples of previously established cancer targets include the classical restriction or reduction of the iron supply, inhibition of transferrin iron delivery and inhibition of ribonucleotide reductase in DNA synthesis, the high antioxidant potential by inhibiting free radical formation etc.." (PMID 36902402, 2023). "In addition, most cancer cells exhibit an overexpression of certain receptors such as transferrin (Tf), folate (FRα), etc., which play a crucial role in cell functions, cellular proliferation (Tf), and regulating the cellular uptake of folate molecules (FRα)." (PMID 36986861, 2023). "High O2 levels artificially increase transferrin production in cancer cells to survive." (PMID 36769044, 2023). "Furthermore, DDIT3 overexpression promoted an enrichment in cancer-related signatures, indicating a potential oncogenic role of this TF." (PMID 36494342, 2022).